CX3CR1 (C-X3-C motif chemokine receptor 1)
Diseases named in the same sentence as CX3CR1 in open-access papers (continued):
Sharing a sentence is not in itself a finding about the gene and the disease.
Neonatal sepsis (4 papers, 2022 to 2026). Systemic inflammatory response to infection in newborn babies. "In this study, we evaluated the diagnostic and prognostic accuracy of transcriptional (CX3CR1, CD74) and proteic (IL6, IL10, IP-10, PCT) biomarkers and their association with clinics and maternal risk factors for neonatal sepsis." (PMID 36509812, 2022). "Accuracy of transcriptional (CD74, CX3CR1), proteic (PCT, IL-6, IL-10, IP-10) biomarkers and clinical characteristics to diagnose and prognose neonatal sepsis were measured." (PMID 36509812, 2022). "There are no data on value of CD74 and CX3CR1 for the prognosis or diagnosis of neonatal sepsis, which hamper current use of these biomarkers in neonates and children." (PMID 36509812, 2022). "Notably, S100A9 was reported to regulate the intestinal environment: Mice lacking S100A9 displayed reduced CX3CR1 protein levels, IL10 and TGF mRNA expression, and fewer T‐reg cells in intestinal tissues, accompanied by a higher risk of fatal neonatal sepsis." (PMID 41542228, 2026).
non-alcoholic steatohepatitis (4 papers, 2023 to 2025). "There is evidence that the interaction of CX3CL1 with its specific receptor CX3CR1 is involved in the development of non-alcoholic steatohepatitis and in the process of skin wound healing through chemotactic recruitment of macrophages and regulation of their migration and polarization." (PMID 38283363, 2023). "Thus, we speculate that the enrichment state of CX3CR1 in non-alcoholic steatohepatitis may undergo alterations during disease progression." (PMID 40918148, 2025).
prion disease (4 papers, 2012 to 2018). A transmissible disease that is caused by a protein that is able to induce abnormal folding of normal cellular proteins, leading to characteristic spongiform brain changes, which are associated with neuronal loss without an inflammatory response. "We have demonstrated that loss of Cx3cr1 results in an acceleration of onset of prion disease with three distinct prion strains (Chandler/RML, ME7 and MRC2) suggesting that intact Cx3cl1/Cx3cr1 signalling is partially protective in prion disease." (PMID 24655482, 2014). "We have shown that Cx3cr1 deficiency results in an acceleration in the onset of the clinical signs of prion disease, as illustrated by shorter incubation times, with three different prion strains." (PMID 24655482, 2014). "Onset of diagnostic signs of prion disease was significantly earlier in Cx3cr1-/- mice relative to controls for all three prion strains." (PMID 24655482, 2014). "In prion disease, microglial proliferation has been suggested to contribute to overall disease progression, however, in different mouse models of neurodegeneration, loss of Cx3cr1 has been shown to either worsen or improve the phenotype depending on the paradigm." (PMID 24655482, 2014). "To investigate the role of Cx3cl1/Cx3cr1 signalling in prion disease we infected Cx3cr1 null mice with three different strains of prions." (PMID 24655482, 2014). "To investigate the role of Cx3cl1/Cx3cr1 neuronal-glial cross talk in prion disease we inoculated female Cx3cr1-/- mice and Balb/c wild type controls intracerebrally with three different mouse-adapted prion strains." (PMID 24655482, 2014). "Our results show that for two mouse-adapted scrapie strains (Chandler/RML and ME7) and a mouse-passaged BSE strain (MRC2), Cx3cr1 deficiency shortens the incubation time thereby suggesting that Cx3cl1/Cx3cr1 signalling is partially protective in prion disease." (PMID 24655482, 2014). "Our data suggest a protective role for Cx3cl1/Cx3cr1 cross-talk in prion disease." (PMID 24655482, 2014). "Also, thiazolopyrimidine derivatives are antagonists of CX3CR1 and have been developed as drugs for prion disease therapy." (PMID 23068602, 2012). "Another microglia-related mechanism relevant to prion disease and influenced by ADAM10 is the Cx3cl1/Cx3cr1 signaling complex." (PMID 25654651, 2015).
skin cancer (4 papers, 2023 to 2025). "Consistent with M2-like macrophages in skin tumors, sub-cluster 2 showed high expression of M2-like macrophage markers, including Mgl2, Cx3cr1, Vcam1, Maf, Ccl8, and Cxcl10." (PMID 40282557, 2025). "CX3CL1 expression was also detected in other skin cancer types, along with the infiltration of CX3CR1+ macrophages." (PMID 38903497, 2024).
status epilepticus (4 papers, 2014 to 2022). Status epilepticus is defined as a continuous seizure lasting more than 30 min, or two or more seizures without full recovery of consciousness between any of them. "An additional group of animals received CX3CR1 antibody intracerebroventricularly for 6 weeks after status epilepticus." (PMID 27346214, 2016). "The increase in CX3CR1 in Syn2-/- mice is in line with our recent findings following electrically-induced status epilepticus in rats." (PMID 26177381, 2015). "Moreover, both CX3CL1 and its receptor, CX3CR1, have been shown to be up-regulated in hippocampal neurons after pilocarpine-induced status epilepticus, a condition characterized by excessive glutamatergic excitation." (PMID 25161610, 2014). "Status epilepticus is a more severe seizure model than the handling-induced seizures in the Syn2-/- mice, which may explain why we, in the current study, did not detect a strong seizure-induced increase in CX3CR1 expression in the tonic-clonic phase." (PMID 26177381, 2015).
subarachnoid hemorrhage (4 papers, 2020 to 2025). A serious neurological disorder characterized by intracranial hemorrhage into the subarachnoid space. "Accumulation of macrophages positive for CCR2 and CX3CR1 was found in all periods after subarachnoid hemorrhage as well as after the application of artificial cerebrospinal fluid." (PMID 39839349, 2024).
Ureteral obstruction (4 papers, 2017 to 2025). Obstruction of the flow of urine through the ureter. "In contrast, the dendritic cell-independent kidney fibrosis model of unilateral ureteral obstruction was exacerbated via local proliferation of profibrotic macrophages in CX3CR1-deficient mice." (PMID 38702742, 2024). "have observed that enhanced expression of CX3CR1 accelerates fibrosis in unilateral ureteral obstruction." (PMID 40046045, 2025).
uveitis (4 papers, 2018 to 2025). An inflammatory process affecting a part of or the entire uvea. "Accordingly, uveitis-associated CX3CR1+ DC3s described in this study exhibit similar phenotypical and functional features." (PMID 37042831, 2023). "For instance, metaDEGs of the uveitis only group comprise genes that are involved in the innate immune response, such as chemokine receptors (CX3CR1, CCR1, and CCR2), and Toll-like receptors (TLR4, TLR7, TLR8, and the TLR4 homologous receptor, CD180)." (PMID 40270958, 2025). "(G) Manual gating strategy of CD1c+ DC subsets based on CD36 and CX3CR1 in PBMCs in uveitis cases and controls." (PMID 37042831, 2023). "The black module was associated with non-infectious uveitis in cohort II (GS for uveitis >0.25) and CX3CR1 was also the hub gene for this module (Black Module Membership, p = 5.9 × 10−22)." (PMID 37042831, 2023). "We constructed co-expression networks that identified a robust gene module associated with non-infectious uveitis in patients that helped identify a CX3CR1-positive CD1c+ DC subset." (PMID 37042831, 2023). "We speculated that CX3CR1+ DC3s are important in the disease mechanisms of uveitis and may be found at increased abundance in the eye during active uveitis." (PMID 37042831, 2023). "A CX3CR1 gene module in CD1c+ dendritic cells (CD1c+ DC) is associated with non-infectious uveitis." (PMID 37042831, 2023). "Moreover, Th17‐related monocytes that highly express lncRNA XIST, CLEC10A, CX3CR1, and THBS1, which are considered critical alarmins that induce inflammation, may be the most feasible hub genes for AS‐associated uveitis and have been found to participate in Th17 cell differentiation." (PMID 39473904, 2024). "Single-cell analysis supported that CD1c+ DCs in eye fluid of patients with non-infectious uveitis contain also a population that has a gene profile reminiscent of CX3CR1+ DC3s, with relatively higher levels of CX3CR1, CD36, CCR2, and lower levels of RUNX3." (PMID 37042831, 2023). "Comparison between patients and controls corroborated that the frequency of manual gated CD36+CX3CR1+ DC3s were decreased in the blood of non-infectious uveitis patients (Welch t-test, p = 0.029)." (PMID 37042831, 2023). "CX3CR1+ DC3s are decreased in the blood of patients with non-infectious uveitis." (PMID 37042831, 2023). "Comparison of classical monocytes between HC and uveitis patients revealed that common monocytic markers, e.g., CCR2, CX3CR1, HLA-DR, HLA-ABC, IL-6, IL-1β, and TNF-α were not affected (data not shown)." (PMID 30105034, 2018).
vasculitis (4 papers, 2015 to 2021). "Therefore, there is a possibility that the tonsillar CD8+ CX3CR1+ cells which invade the glomeruli express its ligand fractalkine, causing vasculitis." (PMID 30957421, 2019). "Of particular relevance for KD vasculitis, the expression of CX3CR1 on NCM and our scRNAseq data) allows them to closely interact with the vasculature." (PMID 34632327, 2021). "Moderate grades are characterised by multiple small focal retinal lesions with moderate vasculitis affecting all retinal vessels evident in brightfield and as Cx3cr1-GFP+ perivenular infiltrates with an absence of fluorescein leakage." (PMID 25623142, 2015). "Mild disease is characterized by swelling of the optic nerve head and mild vasculitis or perivenular cuffing, both evident due to accumulations of Cx3cr1-GFP+ myeloid cells." (PMID 25623142, 2015).
ZIKV infection (4 papers, 2018 to 2021). "Furthermore, ZIKV infection resulted in upregulation of the expression of the gene encoding for CX3CR1, a chemokine receptor known to regulate functional synapse plasticity and signaling between microglial cells." (PMID 31620112, 2019). "Even without specific in vitro antigenic stimulation, DENV, ZIKV, and DENV/ZIKV infections induced expression of CCR5, CX3CR1, and CXCR3 on CD4+ and CD8+ T cells, indicating an activated status of these cells." (PMID 29282904, 2018). "DENV and ZIKV infections and DENV/ZIKV coinfections similarly induced expression of CCR5, CX3CR1, and CXCR3 on CD4 and CD8 T cells." (PMID 29282904, 2018). "However, the role of CX3CR1 and its ligand CX3CL1 during ZIKV infection and its effect on the interaction between neurons and microglia at the synapse have not been identified yet." (PMID 30359409, 2018).
allergic disease (3 papers, 2013 to 2024). An immune response that occurs following re-exposure to an innocuous antigen, and that requires the presence of existing antibodies against that antigen. "In support of this postulate, CX3CR1 expression was downregulated from monocytes to AMØs, as assessed by the analysis of CX3CR1-eGFP mice during HDM allergy." (PMID 37234176, 2023).
amnesia (3 papers, 2022 to 2026). Pathologic partial or complete loss of the ability to recall past experiences ( AMNESIA, RETROGRADE) or to form new memories ( AMNESIA, ANTEROGRADE). "Further, we found that after hypobaric hypoxia exposure, CX3CR1-deficient mice showed less amnesia, less synaptic loss in the CA1 region, and less increase in M1 microglia, compared to their wildtype siblings." (PMID 37234914, 2023). "Also, inhibition of microglial CX3CR1 results reproduced the same effect on infantile amnesia, giving us confidence in our findings." (PMID 41557596, 2026). "We sought to investigate the potential role of CX3CL1-CX3CR1 signaling on infantile amnesia, using JMS-17-2, a potent and selective antagonist of CX3CR1." (PMID 41557596, 2026).
Autoimmunity (3 papers, 2018 to 2025). The occurrence of an immune reaction against the organism's own cells or tissues. "E6011 suppresses the leukocyte infiltration into intrahepatic bile ducts in patients with PBC by inhibiting FKN/CX3CR1 axis, and therefore has the potential to manipulate autoimmunity itself." (PMID 40226574, 2025).
B cell lymphomas (3 papers, 2014 to 2020). "Here we review the different effects of the CX3CL1/CX3CR1 axis in several inflammatory and neurodegenerative diseases and in cancer, with emphasis on human B cell lymphomas." (PMID 24799766, 2014). "In studies by other groups, CX3CR1 expression was investigated in different types of B cell lymphomas by reverse transcriptase-polymerase chain reaction (RT-PCR), immunohistochemistry, and flow cytometry." (PMID 24799766, 2014). "In particular, the overexpression of CX3CR1 in B cell lymphoma and B-CLL in humans suggests that an upregulation of this receptor due to RRV infection may also be associated with cancer development in RM." (PMID 32017809, 2020).
bipolar disorder (3 papers, 2023 to 2025). A disorder of the brain that causes unusual shifts in mood, energy, activity levels and the ability to carry out day-to-day tasks. "Two key hub genes (CX3CR1 and ST6GAL1) were identified as biomarkers for arteriosclerosis in bipolar disorder patients." (PMID 41141090, 2025). "While a lower CX3CR1 expression has been found in patients with bipolar disorder, changes in the connectivity of brain regions related to mood regulation have been observed in mice lacking CX3CR1." (PMID 36644710, 2023).
bladder cancer (3 papers, 2016 to 2023). "The current study focused on investigating CX3CR1 as a potential predictive biomarker to measure bladder cancer responses to OncoTherad® (MRB-CFI-1) immunotherapy." (PMID 38139364, 2023). "Finally, some of the dysregulated proteins found in this study have not been reported previously in bladder cancer, including NEP, Factor XIIIB, PSTPIP1, TFIIHp89 and CX3CR1." (PMID 27626805, 2016).
bone cancer (3 papers, 2014 to 2021). A primary or metastatic malignant neoplasm affecting the bone or articular cartilage. "In a bone cancer model, the development of pain occurs concurrently with microgliosis and an increase in the expression of microglial CX3CR1 and p-p38." (PMID 33858422, 2021). "The same effect is true for the development of bone cancer pain; the development of pain in animals with experimental bone cancer occurs concurrently with microgliosis and an increase in the expression of microglial CX3CR1 and p-p38." (PMID 24847207, 2014).
bone metastasis (3 papers, 2020 to 2025). Transfer of a neoplasm from its primary site to bones. "Fractalkine/CX3CR1 has been associated with bone metastasis in PC." (PMID 33195424, 2020).
brain infarcts (3 papers, 2021 to 2024). "Similarly, the microglia in CX3CR1-deficient mice have more ramified morphologies, tend to develop anti-inflammatory phenotype polarization, and cause smaller brain infarcts." (PMID 33771213, 2021). "After transient occlusion of the middle cerebral artery (MCAO), Cx3cr1GFP/GFP mice exhibited reduced areas of brain infarcts, reduced number of apoptotic cells and infiltrating leucocytes, and reduced blood–brain barrier (BBB) damage compared with Cx3cr1+/GFP and Cx3cr1+/+ mice." (PMID 37818457, 2023).
brain tumor (3 papers, 2016 to 2021). "The GL261/CX3CR1 model proposed in our study also provided brain tumor images of living animals." (PMID 26856327, 2016).
bronchiolitis (3 papers, 2012 to 2024). Inflammation of the bronchioles characterized by swelling of the bronchioles and mucus accumulation. "People carrying the M280 polymorphic variant of CX3CR1 tend to present with more severe cases of bronchiolitis in response to RSV." (PMID 39337288, 2024). "In our data, the best variant near the SNP that was previously reported to be associated with bronchiolitis was in CX3CR1 intron (p = 5.7 × 10−5)." (PMID 28139761, 2017).
cardiac hypertrophy (3 papers, 2021 to 2025). "CX3CR1 has been suggested to be a prerequisite for the development of cardiac hypertrophy and left ventricular dysfunction in mice upon transverse aortic constriction." (PMID 41158506, 2025). "Here, the authors demonstrate that Fraktalkine-receptor CX3CR1 is a prerequisite for the development of cardiac hypertrophy and left ventricular dysfunction in a mouse model of transverse aortic constriction (TAC)." (PMID 33411754, 2021). "Antagonising CX3CR1 markedly reduces the development of cardiac hypertrophy." (PMID 40682481, 2025). "While Wt animals showed a significant increase of aldolase expression 3 and 6 days after TAC, the expression in Cx3cr1GFP/GFP mice did not change, corroborating the finding that cardiac hypertrophy is attenuated in the absence of CX3CR1 signaling." (PMID 33411754, 2021).
colon adenocarcinoma (3 papers, 2021 to 2022). "The results revealed that the levels of CX3CR1 were differentially expressed in various cancer types, including colon adenocarcinoma (COAD) (P < 0.001)." (PMID 35140706, 2021).
deep vein thrombosis (3 papers, 2022 to 2025). "In addition, increased levels of monocytic CX3CR1 expression in HNSCC patients ˃ 65 years of age may be involved in a known increased risk of cancer-associated thrombosis in older patients." (PMID 35625386, 2022). "In patients with idiopathic deep vein thrombosis (DVT), CX3CR1-expressing platelet-bound CD8 + lymphocytes are markedly increased and have been proposed as prognostic markers for adverse cardiovascular events." (PMID 41210882, 2025). "Inhibition of CX3CL1/CX3CR1 in a mouse model of deep vein thrombosis delays thrombolysis and may have the side effect of exacerbating DVT." (PMID 40508161, 2025).
eosinophilia (3 papers, 2005 to 2021). "Therefore, it is possible that this immunogen has the potential to induce both protective antibodies inhibiting interaction of RSV-G with the CX3CR1 and to promote proinflammatory environment in the form of high eotaxin secretion and eosinophilia." (PMID 30142227, 2018).
fungal infection (3 papers, 2021 to 2025). "Polymorphism in the CX3CR1 gene (C-X3-C motif chemokine receptor 1, encoding chemokine receptor) is associated with fungal infection in the gut, and it plays an important role in antifungal activity through activation of Th17 cells and IgG antibody response." (PMID 34490039, 2021). "CX3CR1+ mononuclear phagocytes (CX3CR1+ MNPs) are key mediators in orchestrating the Th17 immune response against fungal infections." (PMID 40284630, 2025). "Using Cx3cr1-CreER-iDTRflox mice, we found that depletion of CX3CR1hiCD45int microglia was maintained during fungal infection." (PMID 37938547, 2023).
Gliosis (3 papers, 2014 to 2025). Gliosis is the focal proliferation of glial cells in the central nervous system. "Overall, for Chandler/RML inoculated mice, the patterns of spongiosis, gliosis and PrP distribution were the same for both wild type and Cx3cr1-/- groups." (PMID 24655482, 2014). "Gliosis and CX3CL1/CX3CR1 expression were also analyzed in the anterior cingulate cortex (ACC) and periaqueductal gray matter (PAG) since they are supraspinal structures involved in pain perception and modulation." (PMID 36056079, 2022).
helminth infection (3 papers, 2021 to 2025). "One study tracked CX3CR1+CD4+ T cells in helminth infection models, identifying them as an activated, tissue-homing population with diverse cytokine production capacities." (PMID 40634636, 2025). "Targeted deletion of BCL6 within this subset reduces the frequency of CX3CR1+CD4+ T cells during infection, underscoring the role of BCL6 in sustaining Th2 responses to helminth infections." (PMID 40634636, 2025).